AGO3 (argonaute RISC catalytic component 3)
Description:
Required for RNA-mediated gene silencing (RNAi). Binds to short RNAs such as microRNAs (miRNAs) and represses the translation of mRNAs which are complementary to them. Proposed to be involved in stabilization of small RNA derivates (siRNA) derived from processed RNA polymerase III-transcribed Alu repeats containing a DR2 retinoic acid response element (RARE) in stem cells and in the subsequent siRNA-dependent degradation of a subset of RNA polymerase II-transcribed coding mRNAs by recruiting a mRNA decapping complex involving EDC4. Possesses RNA slicer activity but only on select RNAs bearing 5'- and 3'-flanking sequences to the region of guide-target complementarity.
Synonyms: hAgo3; EIF2C3; FLJ12765
Tractability: PROTAC: UniProt records ubiquitination sites on it; ubiquitination databases record sites on it; its protein half-life has been measured.
Gene: Protein-coding gene on chromosome 1 (35,930,696 to 36,072,500, forward strand). Ensembl gene ENSG00000126070.
Subcellular location: Cytoplasm, P-body
Subcellular location (Human Protein Atlas): Cytoplasmic bodies; Cytosol; Nucleoplasm
Pathways (Reactome):
Gene expression (Transcription): MicroRNA (miRNA) biogenesis; Post-transcriptional silencing by small RNAs; RUNX1 regulates genes involved in megakaryocyte differentiation and platelet function; Regulation of NPAS4 mRNA translation; Regulation of RUNX1 Expression and Activity; Small interfering RNA (siRNA) biogenesis; Transcriptional Regulation by VENTX
Signal Transduction: Ca2+ pathway; Competing endogenous RNAs (ceRNAs) regulate PTEN translation; Estrogen-dependent gene expression; MAPK6/MAPK4 signaling; MTOR signalling; NR1H3 & NR1H2 regulate gene expression linked to cholesterol transport and efflux; Pre-NOTCH Transcription and Translation; Regulation of PTEN mRNA translation; TGFBR3 expression
Cell-Cell communication: Regulation of CDH1 mRNA translation by microRNAs; Regulation of CDH11 mRNA translation by microRNAs
Cellular responses to stimuli: Oncogene Induced Senescence; Oxidative Stress Induced Senescence
Developmental Biology: Regulation of MITF-M-dependent genes involved in apoptosis
Disease: Nuclear events stimulated by ALK signaling in cancer
Immune System: Regulation of PD-L1(CD274) translation
Gene Ontology:
Molecular function: double-stranded RNA binding; endoribonuclease activity, cleaving miRNA-paired mRNA; miRNA binding; protein binding; RNA binding; RNA endonuclease activity; single-stranded RNA binding; nucleic acid binding
Biological process: miRNA processing; miRNA-mediated gene silencing by inhibition of translation; miRNA-mediated gene silencing by mRNA destabilization; mRNA catabolic process; pre-miRNA processing; regulation of stem cell proliferation; RISC complex assembly; siRNA-mediated gene silencing by mRNA destabilization; regulatory ncRNA-mediated post-transcriptional gene silencing; positive regulation of gene expression; positive regulation of non-canonical NF-kappaB signal transduction; regulatory ncRNA-mediated gene silencing
Cellular component: cytoplasm; cytoplasmic ribonucleoprotein granule; membrane; RISC complex; RISC-loading complex; cytosol; condensed nuclear chromosome; P-body
Genetic constraint (gnomAD): Loss-of-function variants: 15 observed, 99.76 expected, observed/expected ratio (o/e) 0.15, 90% interval 0.1 to 0.23. The upper end of that interval is the gene's LOEUF score, 0.23, which puts it in group 1 of 6, group 1 being the genes least tolerant of losing a copy. Missense variants: 533 observed, 1,095.5 expected, observed/expected ratio (o/e) 0.49, 90% interval 0.45 to 0.52. Synonymous variants: 338 observed, 370.82 expected, observed/expected ratio (o/e) 0.91, 90% interval 0.83 to 1.
Homologues: Orthologues: chimpanzee AGO3 (100% identical), macaque AGO3 (100% identical), dog AGO3 (99% identical), rabbit AGO3 (99% identical), rat Ago3 (99% identical), mouse Ago3 (99% identical), pig AGO3 (98% identical), tropical clawed frog EIF2C3 (97% identical), zebrafish ago3a (97% identical), guinea pig AGO3 (96% identical), zebrafish ago3b (95% identical), Caenorhabditis elegans alg-3 (40% identical), and 9 more. Paralogues in human: AGO1 (85% identical), AGO4 (82% identical), AGO2 (80% identical).